CNGB3 (cyclic nucleotide gated channel subunit beta 3)
Description:
Pore-forming subunit of the cone cyclic nucleotide-gated channel. Mediates cone photoresponses at bright light converting transient changes in intracellular cGMP levels into electrical signals. In the dark, cGMP levels are high and keep the channel open enabling a steady inward current carried by Na(+) and Ca(2+) ions that leads to membrane depolarization and neurotransmitter release from synaptic terminals. Upon photon absorption cGMP levels decline leading to channel closure and membrane hyperpolarization that ultimately slows neurotransmitter release and signals the presence of light, the end point of the phototransduction cascade. Conducts cGMP- and cAMP-gated ion currents, with permeability for monovalent and divalent cations.
Synonyms: ACHM1; formerly ACHM3; RMCH
Tractability: Small molecule: a structure with a bound ligand is known; it belongs to a druggable protein family. Antibody: UniProt places it where antibodies can reach, with high confidence; its Gene Ontology location is reachable by antibodies, with high confidence; UniProt predicts a signal peptide or a membrane-spanning region. PROTAC: ubiquitination databases record sites on it.
Gene: Protein-coding gene on chromosome 8 (86,553,977 to 86,743,675, reverse strand). Ensembl gene ENSG00000170289.
Subcellular location: Cell membrane
Gene Ontology:
Molecular function: cGMP binding; intracellularly cAMP-activated cation channel activity; intracellularly cGMP-activated cation channel activity; intracellularly cyclic nucleotide-activated monoatomic cation channel activity; monoatomic ion channel activity
Biological process: monoatomic cation transport; visual perception; monoatomic cation transmembrane transport; signal transduction; monoatomic ion transport; transmembrane transport
Cellular component: intracellular cyclic nucleotide activated cation channel complex; plasma membrane; transmembrane transporter complex; cone photoreceptor disc membrane; photoreceptor outer segment; photoreceptor outer segment membrane; membrane
Genetic constraint (gnomAD): Loss-of-function variants: 67 observed, 78.68 expected, observed/expected ratio (o/e) 0.85, 90% interval 0.7 to 1.04. The upper end of that interval is the gene's LOEUF score, 1.04, which puts it in group 4 of 6, group 1 being the genes least tolerant of losing a copy. Missense variants: 897 observed, 884.74 expected, observed/expected ratio (o/e) 1.01, 90% interval 0.96 to 1.07. Synonymous variants: 302 observed, 312.12 expected, observed/expected ratio (o/e) 0.97, 90% interval 0.88 to 1.06.
Gene-disease validity (ClinGen):
ClinGen rates the evidence that CNGB3 causes each of these diseases.
CNGB3-related retinopathy (autosomal recessive): Definitive. A retinopathy caused by biallelic variants in the CNGB3 gene.
Homologues: Orthologues: chimpanzee CNGB3 (99% identical), macaque CNGB3 (95% identical), pig CNGB3 (76% identical), dog CNGB3 (76% identical), rabbit CNGB3 (76% identical), guinea pig CNGB3 (63% identical), rat Cngb3 (60% identical), mouse Cngb3 (59% identical), zebrafish cngb3.1 (43% identical), tropical clawed frog cngb3 (40% identical), zebrafish cngb3.2 (40% identical), Drosophila melanogaster CngB (28% identical), and 10 more. Paralogues in human: CNGB1 (47% identical), CNGA1 (22% identical), CNGA2 (22% identical), CNGA3 (22% identical), CNGA4 (19% identical), HCN4 (19% identical), HCN2 (17% identical), HCN1 (17% identical), HCN3 (16% identical), KCNH2 (15% identical), KCNH1 (15% identical), KCNH7 (15% identical), and 5 more.
Diseases named in the same sentence as CNGB3 in open-access papers:
CNGB3 is named in the same sentence as 39 diseases in open-access papers, as found by Europe PMC text mining. Sharing a sentence is not in itself a finding about the gene and the disease. The quoted sentences say what the papers report.
achromatopsia (80 papers, 2008 to 2025). Achromatopsia (ACHM) is a rare autosomal recessive retinal disorder characterized by color blindness, nystagmus, photophobia, and severely reduced visual acuity due to the absence or impairment of cone function. "CNGA3 and CNGB3 functioned together by forming a heterotetramer cyclic nucleotide-gated (CNG) channel resulting in up to 95% of achromatopsia patients having pathogenic defects in the CNGA3/CNGB3 channel complex (cone CNG channel)." (PMID 40448196, 2025). "Our search yielded 41 patients (24 females; 17 males) with molecularly confirmed CNGB3-associated achromatopsia who had undergone imaging with both FAF devices during the same clinic visit." (PMID 40423615, 2025). "The mutation spectrum of achromatopsia‐associated CNGB3 variants comprises all types of mutations, including those that are straightforward to evaluate in molecular genetic diagnostics, such as frame‐shifting, nonsense, and canonical splice site variants." (PMID 40304364, 2025). "We explored discrepancies between FAF images acquired with two widely used devices, with respect to the central foveal signal, in patients with molecularly confirmed CNGB3-associated achromatopsia." (PMID 40423615, 2025). "Up to 70% of achromatopsia patients carry pathogenic mutations in CNGB3, while another 25% of patient cases have pathogenic CNGA3 variants." (PMID 40448196, 2025). "The phase I/II clinical trial (NCT03001310) tested the safety and efficacy of AAV8-hCARp.hCNGB3 gene replacement therapy on 23 participants (11 adults and 12 children) with CNGB3-associated achromatopsia." (PMID 39273686, 2024). "There are currently five gene therapy clinical trials registered for human patients at the phase I/II stage and for CNGA3 or CNGB3 causing achromatopsia." (PMID 39273686, 2024). "USH2A-associated retinal pathology is the third most common autosomal recessive form of IRD among Russian patients, after Stargardt disease, caused by biallelic variants in the ABCA4 gene and achromatopsia, associated with mutations in the CNGB3 gene." (PMID 39596236, 2024). "A recent phase I/II clinical trial of AAV8-hCARp.hCNGB3 gene replacement therapy in adults and children who have CNGB3-associated achromatopsia demonstrated acceptable safety and improvements in several efficacy assessments with 6 months follow-up." (PMID 39273686, 2024). "Mutations in CNGA3 and CNGB3 are associated with achromatopsia, progressive CRD, and early-onset macular degeneration." (PMID 37446378, 2023). "There are over 100 and 40 mutations identified in CNGA3 and CNGB3, respectively, accounting for 70–80% of the total achromatopsia cases." (PMID 37446378, 2023). "Among them, 80 were affected by MD, 28 by CD (two of them presented with cone dystrophy were found to be affected by achromatopsia with pathogenic variants in CNGB3, a gene included in the cone dystrophy panel) and 28 from CRD." (PMID 35260635, 2022). "The CNGB3 gene encodes the β subunit of the cyclic nucleotide-gated channel in cone photoreceptors; mutations in this gene cause achromatopsia in humans, which is also observed in animals." (PMID 36140707, 2022). "Genetic variants of both CNGA3 or CNGB3 have been reported in humans with achromatopsia (ACHM), cone–rod dystrophy or other disorders such as progressive cone dystrophy." (PMID 35456423, 2022). "Previously, the potency of gene therapy vectors for the treatment of CNGA3- or CNGB3-linked achromatopsia was assessed after subretinal or intravitreal injection of the gene therapy vector in gene-deficient animal models (i.e., mouse or dog)." (PMID 35562929, 2022). "Up to 90% of achromatopsia cases are due to mutations in CNGA3 or CNGB3 with approximately 100 mutations described in each of these genes." (PMID 36584110, 2022). "Here, pathogenic variants in CNGB3 were the most common cause of achromatopsia (ACHM), and variants in CACNA1F were the most prevalent cause of CSNB." (PMID 33749171, 2021).
achromatopsia (continued). "Of interest was the heterozygous CNGB3 c.1148del variant, previously associated with achromatopsia, an autosomal recessive cone photoreceptor disease." (PMID 33776059, 2021). "CNGA3 and CNGB3 mutations are the two most common causes and are responsible for approximately 80% of all achromatopsia cases." (PMID 34360834, 2021). "A 140-kb deletion and a missense mutation in CNGB3 occurs in achromatopsia-affected dogs of multiple breeds." (PMID 34830323, 2021). "The hiPSC line was generated from a patient with achromatopsia due to a homozygous deletion (c.1148delC) in CNGB3, encoding the beta subunit of a cone-specific cyclic nucleotide-gated (CNG) channel." (PMID 33882303, 2021). "More recently however, a somatic, macular knockout model of CNGB3-associated achromatopsia has been generated in monkeys using AAV9-mediated delivery of a CRISPR/Cas9-based construct." (PMID 33815052, 2021). "Beside 34 non-coding variants, all located in the critical region on chromosome 14, this analysis identified a single homozygous private protein-changing variant in CNGB3, a known candidate gene for achromatopsia." (PMID 34830323, 2021). "Current studies include Phase 1/2 trials in CNGA3- and CNGB3-associated achromatopsia (Sponsors: AGTC; MeiraGTx; STZ eyetrial)." (PMID 34768969, 2021). "Mutations in CNGB3 are responsible for at least 50% of achromatopsia cases in humans, making it an ideal target for therapies." (PMID 32260251, 2020). "There are several gene therapies reported in achromatopsia animal models: sheep, and mouse models with CNGA3-related achromatopsia, mouse and canine models with CNGB3 mutations, and a mouse model with a genetic defect in the GNAT2 gene." (PMID 32953936, 2020). "Mutations in genes encoding the channel subunits CNGA3 and CNGB3 account for ∼80% of all cases of achromatopsia and are associated with progressive cone dystrophies." (PMID 31182474, 2019). "Treatment of dogs with achromatopsia secondary to CNGB3 mutation have shown durable rescue of cone function after viral-mediated gene replacement for at least 33 months." (PMID 30667376, 2019). "Mutations in the cone photoreceptor CNG channel subunits CNGA3 and CNGB3 are associated with achromatopsia and cone dystrophies." (PMID 31182474, 2019). "Mutations in CNGB3, the beta subunit of the cyclic nucleotide-gated channels in cones, are associated with loss of cone function leading to achromatopsia (day blindness) in humans and in certain canine breeds." (PMID 28993665, 2017). "Although a greater variety of specific mutations in CNGA3 have been linked to achromatopsia compared to mutations in CNGB3, mutations in CNGA3 only account for 20–30% of the known cases." (PMID 26106334, 2015). "Mutations in CNGA3 and CNGB3, which encode similar subunits in cone photoreceptor channels, are a major cause of achromatopsia." (PMID 25650393, 2015). "Day blindness, an achromatopsia-like phenotype, was identified in German shorthair pointer dogs with an Asp to Asn missense mutation at position 262 of the CNGB3 subunit (B3-D262N)." (PMID 24586388, 2014). "In this study, we have found that two mutations in CNGB3, which were linked previously to achromatopsia, progressive cone dystrophy, and/or macular degeneration, increased susceptibility to cell death." (PMID 23805033, 2013). "We have examined the cellular consequences of two different CNGB3 mutations linked to achromatopsia, cone dystrophy, and/or macular degeneration in humans." (PMID 23805033, 2013). "Mutations in the two subunits (CNGA3, CNGB3) of cone photoreceptor cyclic nucleotide-gated (CNG) channels account for approximately 75% of all cases of complete achromatopsia." (PMID 22509403, 2012). "Notably, CNGA3 and CNGB3 function together by forming a heterotetramer cyclic nucleotide-gated (CNG) channel resulting in up to 95% of achromatopsia patients carrying pathogenic defects in the CNGA3/CNGB3 channel complex (cone CNG channel)." (PMID 40448196, 2025).
achromatopsia (continued). "CNGB3 is the commonest gene associated with achromatopsia in our and several other cohorts." (PMID 40423615, 2025). "Results from 3 of the trials have been formally published in peer‐reviewed journals: these have related to therapies for CNGA3‐associated achromatopsia (with 3‐year results published), CNGB3‐associated achromatopsia (6 month results published) and GUCY2D‐associated LCA." (PMID 40013354, 2025). "However, scientists have found, in CNGB3-associated recessive achromatopsia, certain disease-associated mutations caused “gain-of-function” alterations." (PMID 39171529, 2024). "Potential phenocopies of the optical gap appearance on OCT imaging include achromatopsia (associated with CNGA3 or CNGB3 mutations), cone dystrophy (associated with GUCY2D or other genes), RP1L1-associated occult macular dystrophy, and acquired diseases such as solar retinopathy." (PMID 38066771, 2023). "However, CNGB3 mutations cause achromatopsia 3, which is characterized by loss of color vision and photoreceptor degeneration." (PMID 37691820, 2023). "Mutations in the genes encoding the cone CNG channel (CNGA3 and CNGB3) lead to achromatopsia." (PMID 36830806, 2023). "Cngb3 is a cone photoreceptor with a cGMP-gated channel, which is associated with achromatopsia." (PMID 34779479, 2021). "Interestingly, the bovine homolog of CNGB3, a gene that causes achromatopsia in other species, maps to that genome region at 76 Mb." (PMID 34830323, 2021). "These experiments show the Tri-Asp motif is necessary for proper cone CNG channel formation, but raises the question why mutations in CNGB3 result in the loss of cone function and achromatopsia when CNGA3 can form a functioning homomeric channel in the absence of CNGB3." (PMID 32260251, 2020). "In contrast to our observations, a recent study in dogs affected with achromatopsia due to mutations in the CNGB3 gene did show the highest protection of S cone opsin expression in the superior central area attached to non-pigmented RPE (corresponding to our region 2)." (PMID 24466015, 2014). "In dogs, two different CNGB3 mutations were identified that result in the achromatopsia phenotype." (PMID 23601474, 2013). "Four of the CNG channel genes are linked to inherited retinal disorders (IRD): mutations in CNGA1 and CNGB1 are known to cause retinitis pigmentosa (RP) and mutations in CNGA3 and CNGB3 cause achromatopsia (ACHM)." (PMID 36830806, 2023). "However, we excluded the likelihood of a second CNGB3 variant as the electrophysiological results make a diagnosis of achromatopsia unlikely; however, the testing revealed a slightly depressed b-wave, indicating a dysfunction between photoreceptors and the interneurons." (PMID 33776059, 2021). "Clinical trials in patients with geographic atrophy, retinitis pigmentosa or CNGB3-achromatopsia have shown that the NT-501 implants are well tolerated and provide long-term intraocular delivery of the cytokine." (PMID 40358167, 2025). "Achromatopsia is an autosomal recessive genetic disease, and 95% of achromatopsia patients carry pathogenic mutations in the CNGA3 and CNGB3 genes." (PMID 40448196, 2025). "To date, pathogenic variants in six genes have been associated with achromatopsia, five of which play vital roles in the cone phototransduction cascade (i.e., CNGA3, CNGB3, GNAT2, PDE6C, PDE6H, and ATF6)." (PMID 40448196, 2025). "CNGB3 is the major locus for achromatopsia in patients of European origin or descent, and truncation variants predominate; the p.(Thr383Ilefs*) is a frequent founder mutation." (PMID 40013354, 2025). "Pathogenic variants in different genes such as CNGA3, CNGB3, GNAT2, PDE6H, ATF6 and PDE6C have been reported to be relevant to COD, cone-rod dystrophy (CORD) and achromatopsia (ACHM) diseases." (PMID 38956522, 2024).
achromatopsia (continued). "Each gene therapy contains either CNGB3 or CNGA3, based on the reasoning that mutations in these genes affect 80% of achromatopsia patients, and were packaged into an AAV capsid and then delivered by a subretinal injection after vitrectomy." (PMID 39273686, 2024). "Currently, six genes that cause achromatopsia have been discovered, including CNGA3, CNGB3, GNAT2, PDE6C, PDE6H and ATF6." (PMID 38298913, 2024). "We identified variants believed to be disease causing in five of the known achromatopsia genes: CNGA3; CNGB3; GNAT2; PDE6C and PDE6H; and novel variants were identified in CNGB3 and PDE6C." (PMID 36980963, 2023). "Achromatopsia is a cone-dystrophy commonly studied, with many studies investigating the Cnga3−/−, Cngb3−/− models which make up approximately 30% and 50% of achromatopsia cases, respectively, as well as the cone photoreceptor function loss 1 (Cpfl) model." (PMID 35054919, 2022). "Using a novel multimodal approach, we demonstrate for the first time that gene therapy can successfully activate dormant cone-mediated pathways in children with achromatopsia (CNGA3- and CNGB3-associated, 10–15 years)." (PMID 35998912, 2022). "Other activated caspases such as caspase-7 and caspase-12 have also been identified in the Cnga3−/− retina as well as in the Cngb3−/− mouse model (another model of achromatopsia), suggesting apoptosis is present in primary cone death." (PMID 35054919, 2022). "The CNGA3 and CNGB3 genes contribute to approximately 65-80% of achromatopsia cases, and therefore, research has been focused on the Cnga3−/− and Cngb3−/− animal models to study primary cone degeneration." (PMID 35054919, 2022). "To date, six genes (ATF6A, CNGA3, CNGB3, GNAT2, PDE6C, and PDE6H) are known to cause achromatopsia, with mutations in CNGA3 and CNGB3 responsible for more than 90% of cases." (PMID 35562929, 2022). "In conclusion, we have evidence for the occurrence of a breed-specific novel CNGB3-related form of recessively inherited achromatopsia in Original Braunvieh cattle which we have designated OH1 showing an allele frequency of the deleterious allele of ~8%." (PMID 34830323, 2021). "Pathogenic variants in six genes (CNGA3, CNGB3, GNAT2, ATF6, PDE6C, and PDE6H) have been identified in humans with achromatopsia (OMIM 216900)." (PMID 34830323, 2021). "Herein, we generated three cynomolgus macaques with macular in situ knockout by subretinal delivery of an adeno-associated virus (AAV)-mediated CRISPR-Cas9 system targeting CNGB3, the gene responsible for achromatopsia." (PMID 32953936, 2020). "Its neuroprotective effects have been evaluated in patients with dry AMD, CNGB3-achromatopsia, glaucoma, retinitis pigmentosa, and macular telangiectasia type 2 (MacTel 2)." (PMID 32629980, 2020). "In conclusion, we, for the first time, generated an NHP model with a partial knockout of the CNGB3 gene in the macular cones, exhibiting cone dysfunction consistent with achromatopsia in human patients." (PMID 32953936, 2020). "In a phase I/II clinical trial sponsored by Applied Genetic Technologies Corporation, AAV was used to deliver CNGB3 for the successful treatment of achromatopsia." (PMID 31069169, 2019). "Loss of CNGB3 has been associated with loss of its heterotetrameric partner CNGA3 since it regulates the expression of CNGB3 as was shown in the mouse model of CNGA3-achromatopsia before and after gene therapy." (PMID 28993665, 2017). "Mouse models of CNGA3 and CNGB3 achromatopsia showed cone dysfunction and have been used to evaluate the efficacy of gene augmentation therapy." (PMID 25650393, 2015). "Further, the hB3 gene was used successfully for retinal gene augmentation therapy to restore cone function in dogs with CNGB3-achromatopsia confirming proper functioning of cA3+ hB3 channels." (PMID 24586388, 2014). "CNGB3-achromatopsia, or cone degeneration (cd), is also known to occur in two canine breeds, the Alaskan malamute (AM) and the German shorthaired pointer." (PMID 23601474, 2013).